HOPX (HOP homeobox)
Diseases named in the same sentence as HOPX in open-access papers (continued):
Sharing a sentence is not in itself a finding about the gene and the disease.
endometrial cancer (4 papers, 2012 to 2025). Primary or metastatic malignant neoplasm involving the endometrium (mucous membrane that lines the endometrial cavity). "HOPX has been demonstrated to be down-regulated due to its promoter hypermethylation and acts as a tumor suppressor in several cancers, including endometrial cancer." (PMID 32608475, 2020). "In vitro or in vivo tumorigenesis has been repeatedly proven to be suppressed by HOPX gene transfection in esophageal cancer, endometrial cancer, gastric cancer, and pancreatic cancer." (PMID 24287901, 2013). "Other groups also recapitulated the similar finding that HOPX promoter DNA is hypermethylated specifically in endometrial cancer." (PMID 22958219, 2012). "HOPX has been identified as one of the most cancer-specific hypermethylated biomarkers, with hypermethylation detected in 90% of primary gastric tumors, 62.5% (10/16) colorectal, and 69% (9/14) endometrial cancers, the latter was considerably higher than the 39% hypermethylation in our OC samples." (PMID 40002854, 2025). "Of these, c-Fos has been repeatedly described as a HOPX downstream gene in non-colonic cells such as endometrial cancer and regulatory T cells (Treg)." (PMID 24287901, 2013).
skin cutaneous melanoma (4 papers, 2023 to 2025). "As a result, HOPX represents a potential therapeutic target in patients with cutaneous melanoma and has the potential to be used as a diagnostic and prognostic factor." (PMID 37344870, 2023). "Similarly, the association of HOPX expression with drug efficacy was depicted in skin cutaneous melanoma (SKCM)." (PMID 41227363, 2025). "Besides, DSC1 is significantly associated with infiltration by most immune cells; HOPX expression is linked to immune processes and shows high enrichment of T cells, suggesting it could serve as an immune checkpoint in skin cutaneous melanoma." (PMID 41199193, 2025). "In this study, bioinformatics analysis, in vitro experiments, and sequencing validation were used to explore the role of HOPX in cutaneous melanoma for investigation." (PMID 37344870, 2023). "In addition, HOPX may serve as a novel molecular biomarker for skin cutaneous melanoma treatment, which may facilitate the development of novel immunotherapy strategies with high clinical significance in the future." (PMID 37344870, 2023). "In addition, in vitro experiments using human malignant cutaneous melanoma cells showed that HOPX inhibited proliferation, migration, and invasion of A375 cells, promoted apoptosis and S-phase arrest, and may enhance the sensitivity of clinical chemotherapeutic agents." (PMID 37344870, 2023).
choriocarcinoma (3 papers, 2009 to 2025). An aggressive malignant tumor arising from trophoblastic cells. "In choriocarcinoma, ectopic HOPX expression results in cell morphological changes and inhibition of in vivo tumorigenesis." (PMID 41227363, 2025). "The loss of human HOPX (synonyms NECC1 and LAGY) expression evident in choriocarcinoma is thought to be involved in malignant conversion of placental trophoblasts and has lead to the suggestion that HOPX is a candidate tumour suppressor gene." (PMID 19200380, 2009).
head and neck cancer (3 papers, 2016 to 2022). A primary or metastatic malignant neoplasm affecting the head and neck. "Moreover, HOPX plays a critical role in epithelial cell homeostasis and functions as a tumor suppressor in head and neck cancer." (PMID 31666923, 2019).
head and neck squamous cell carcinoma (3 papers, 2020 to 2025). A squamous cell carcinoma that arises from any of the following anatomic sites: lip and oral cavity, nasal cavity, paranasal sinuses, pharynx, larynx, and salivary glands. "In head and neck squamous cell carcinoma (HNSCC), overexpression of HOPX leads to decreased cell proliferation and enhanced sensitivity to UVA-induced apoptosis." (PMID 41227363, 2025).
heart failure (3 papers, 2013 to 2023). Inability of the heart to pump blood at an adequate rate to meet tissue metabolic requirements. "Both HOPX and FHL2 are down-regulated in human heart failure, and may contribute to the dysregulation of SRF-dependent gene expression during pathogenesis." (PMID 23437181, 2013). "A study showed that HOPX expression is reduced and completely absent in severe heart failure." (PMID 38077583, 2023).
pancreatic cancer (3 papers, 2012 to 2022). "Treatment of head and neck, esophageal, and pancreatic cancer cells with demethylating drugs such as 5-aza-2-deoxycytidine restored HOPX expression." (PMID 35681746, 2022). "By positively regulating the subG1 and GO/G1 phases, HOPX reduces DNA synthesis and promotes cell death in pancreatic cancer." (PMID 35681746, 2022). "We have reported that HOPX is frequently methylated in a cancer-specific manner, and functions as a tumor suppressor gene in esophageal, gastric, colon and pancreas cancers in the previous studies." (PMID 31666923, 2019). "In this present study, we for the first time added pancreatic cancer to the list of organs in which HOPX is involved in carcinogenesis." (PMID 22958219, 2012). "In this current study, we for the first time examined methylation level of HOPX and tested the functional relevance in pancreatic cancer (PC)." (PMID 22958219, 2012). "Defective expression of HOPX which is consistent with promoter DNA hypermethylation may explain aggressive phenotype of pancreatic cancer, and intense expression of HOPX in the Langerhans cells may in turn uniquely contribute to pancreatic carcinogenesis." (PMID 22958219, 2012). "Defective expression of HOPX which is consistent with CpG islands promoter DNA hypermethylation may explain aggressive phenotype of pancreatic cancer, and intense expression of HOPX in the Langerhans islet cells may in turn uniquely contribute to pancreatic carcinogenesis." (PMID 22958219, 2012).
sarcoma (3 papers, 2013 to 2025). A usually aggressive malignant neoplasm of the soft tissue or bone. "HOPX exerts a tumor-suppressive function in various types of epithelial-derived carcinoma, while it promotes oncogenic effects in mesenchymal-derived sarcoma, indicating a distinct role of HOPX in the two major types of the malignancy." (PMID 41227363, 2025). "In mesenchymal cell-derived sarcoma, HOPX functions as an oncogene." (PMID 41227363, 2025). "Given the prognostic relevance of HOPX in primary CRC, and findings obtained from basic research on the role of HPOX in cancer not including sarcoma, HOPX is likely implicated in the suppression of metastasis of CRC." (PMID 24287901, 2013).
thyroid cancer (3 papers, 2019 to 2025). "Hypermethylation of the HOPX DNA was identified in patients with thyroid cancer, associated with recurrent/progressive disease and poor clinical outcome." (PMID 41227363, 2025). "On the other hand, it has been shown that HOPX is highly expressed in thyroid cancer and squamous skin cell carcinoma and can promote tumor cell invasion and metastasis." (PMID 37344870, 2023). "Here, we particularly focused on the clinical impact of epigenetic silencing of HOPX in PTC that comprises the majority of thyroid cancer." (PMID 31666923, 2019). "In this study, HOPX expression and the DNA promoter methylation status were assessed in human thyroid cancer tissues and cell lines." (PMID 31666923, 2019). "The promoter methylation of HOPX was observed in five of six human thyroid cancer cell lines." (PMID 31666923, 2019). "HOPX expression was initially examined in 6 human thyroid cancer cell lines." (PMID 31666923, 2019). "Despite that epigenetic DNA modifications may be critical events also in thyroid cancer, the clinical importance and the involved mechanisms of HOPX in thyroid cancer has been elusive." (PMID 31666923, 2019).
cardiomyopathy (2 papers, 2013 to 2020). A disease of the heart muscle or myocardium proper. "HOPX initially reported as a crucial molecule for the maintenance of heart function and was involved in cardiomyopathy, fibrosis, and hypertrophy." (PMID 31934721, 2020). "The extent to which HOPX and FHL2 levels are down-regulated correlates with the development of cardiomyopathy in MHC-CELFΔ severe line males." (PMID 23437181, 2013). "Both alternative splicing changes and down-regulation of HOPX and FHL2 correlate with the development of overt cardiomyopathy in MHC-CELFΔ males, which exhibit partial penetrance of the phenotype." (PMID 23437181, 2013).
colitis (2 papers, 2021 to 2024). Inflammation of the colon. "However, PSTi8-treated female mice had significantly reduced LY6A and HOPX protein levels compared to PBS-treated female mice during colitis (p < 0.05)." (PMID 39684467, 2024). "HOPX-deficient mice do not develop colitis or arthritis in models inducing these inflammatory conditions." (PMID 34386009, 2021). "PSTi8 treatment in males preserved the Lgr5+ cell population while depleting HOPX+ and LY6A+ cells in colitis." (PMID 39684467, 2024).
differentiated thyroid carcinoma (2 papers, 2019 to 2023). Differentiated thyroid carcinoma (DTC), also known as papillary or follicular thyroid carcinoma, is a slow-growing malignancy usually presenting in adults as an asymptomatic thyroid mass. "Hypermethylation of HOPX-β has been reported to be associated with poor survival in patients with differentiated thyroid cancer, and the methylation level of the HOPX promoter in esophageal squamous carcinoma tissue was inversely correlated with patient survival." (PMID 37344870, 2023).
esophageal squamous cell carcinoma (2 papers, 2022 to 2025). Esophageal squamous cell carcinoma (ESCC) is a type of esophageal carcinoma (EC) that can affect any part of the esophagus, but is usually located in the upper or middle third. "Interestingly, HOPX has been ranked second among the top priority genes that undergo methylation in primary esophageal squamous cell carcinoma." (PMID 35681746, 2022).
leukemia (2 papers, 2021 to 2025). A malignant (clonal) hematologic disorder, involving hematopoietic stem cells and characterized by the presence of primitive or atypical myeloid or lymphoid cells in the bone marrow and the blood. "While the expression of the stem‐related gene HOXA10 is not significantly different between NPM1, KMT2Ar, and NUP‐r harboring leukemias, we found that HOPX expression is significantly different between KMT2Ar and NUP‐r in comparison to NPM1." (PMID 41178390, 2025). "We observed an enrichment of HOPX expression among KMT2Ar leukemias in the MK‐V transcriptional identity and among NUP‐r leukemias in the AMTL and MK‐V transcriptional identities." (PMID 41178390, 2025). "When minimizing transcriptional differences through observation of a single transcriptional identity, we observe higher expression of HOPX in KMT2Ar and NUP‐r leukemia." (PMID 41178390, 2025). "HOPX, DOCK1, DNMT3B, MMRN1, and ARHGAP22 genes were reported as important leukemia stem cell markers." (PMID 33225420, 2021).
metastatic disease (2 papers, 2013 to 2021). "This analysis further elucidated that the HOPX methylation value significantly increases during progression from non-metastatic disease (pN0) to metastatic disease (pN1) in CRC." (PMID 24287901, 2013).
non-small cell lung carcinoma (2 papers, 2022 to 2023). A group of at least three distinct histological types of lung cancer, including non-small cell squamous cell carcinoma, adenocarcinoma, and large cell carcinoma. "This study aimed to elucidate a computed tomography (CT) image-based biopsy with a radiogenomic signature to predict homeodomain-only protein homeobox (HOPX) gene expression status and prognosis in patients with non-small cell lung cancer (NSCLC)." (PMID 37190150, 2023).
Papillary thyroid cancer (2 papers, 2019 to 2020). "These previous results prompted us to seek the clinical ramifications of epigenetic silencing of HOPX in papillary thyroid cancer (PTC) which represents the vast majority of thyroid malignancies." (PMID 31666923, 2019). "HOPX promoter methylation is frequent and cancer-specific in papillary thyroid cancer (PTC)." (PMID 31666923, 2019).
prostate carcinoma (2 papers, 2022 to 2025). A carcinoma that arises from epithelial cells of the prostate gland. "As results, high KCTD4 expression, low THBS2 expression, and high ACPP expression were associated with favorable BCRFS of prostate cancer patients; and high expression levels of HOPX, TMEM132A, and ZNF467 were associated with shorter MFS of prostate cancer patients." (PMID 36195908, 2022). "Indeed, HOPX is considered one of the cancer-associated fibroblast (CAF)-related genes, and high expression of HOPX was significantly associated with shorter metastasis-free survival of patients with prostate carcinoma." (PMID 41227363, 2025).
pulmonary fibrosis (2 papers, 2018 to 2022). Chronic progressive interstitial lung disorder characterized by the replacement of the lung tissue by connective tissue, leading to progressive dyspnea, respiratory failure, or right heart failure. "In the present study, HOPX is shown to be upregulated in pmATII cells in BLM model of pulmonary fibrosis in vivo." (PMID 30154568, 2018). "We then investigated HOPX expression in an ATII-ATI trans-differentiation culture model in vitro, in bleomycin-induced mouse model of pulmonary fibrosis in vivo, and by database analyses of expression profiles of IPF lungs in silico." (PMID 30154568, 2018). "Furthermore, we show that DZNep treatment alone or in context of SARS‐CoV or SARS‐CoV‐2 infections reduces abundance of pulmonary fibrosis markers (e.g., SERPINE1, MMP14, and COL4A1) and increases levels of factors with antifibrotic activity (e.g., HOPX, PI3/ELAFIN, and SLPI)." (PMID 35833542, 2022).
Alzheimer disease (1 paper, 2019). A progressive, neurodegenerative disease characterized by loss of function and death of nerve cells in several areas of the brain leading to loss of cognitive function such as memory and language. "These genes were selected for their involvement in cognitive functioning since SCN3B and HOPX were lower expressed and DSP was higher expressed in hippocampal region of patients with Alzheimer’s disease." (PMID 31610812, 2019).
atrial fibrillation (1 paper, 2013). A disorder characterized by an electrocardiographic finding of a supraventricular arrhythmia characterized by the replacement of consistent P waves by rapid oscillations or fibrillatory waves that vary in size, shape and timing and are accompanied by an irregular ventricular response. "We demonstrate the use of our algorithm to predict novel candidate genes for human atrial fibrillation (such as HRH2, ATP4A, ATP4B, and HOPX) and epilepsy (e.g., PAX6 and NKX2-1)." (PMID 23800157, 2013).
Breast invasive carcinoma (1 paper, 2023). "The results showed that HOPX expression was significantly upregulated in 25, including ACC (Adrenocortical carcinoma) (p < 0.001) and BRCA (Breast invasive carcinoma) (p < 0.001), while HOPX expression was much lower in the SKCM tumor group compared to the normal group (p < 0.001)." (PMID 37344870, 2023).
breast tumors (1 paper, 2015). "Similarly, we also observed genes that were hypermethylated at promoter regions but expressed in breast tumors (such as HOPX and THY1)." (PMID 25706888, 2015).
colon cancer (1 paper, 2019). "On the other hand, DLD1 (colon cancer cell line) expresses weak HOPX-α but HOPX-βreactivation significantly increased HOPX-core expression in our previous report." (PMID 31666923, 2019).
Down syndrome (1 paper, 2025). "Another EWAS performed in drops of blood collected at birth in children with Down Syndrome (DS) showed that HOPX, SMIM24, and PPP1R10 were abnormally methylated in children with DS who developed ALL." (PMID 41226303, 2025).
ependymoma (1 paper, 2020). A WHO grade II, slow growing tumor of children and young adults, usually located intraventricularly. "Finally, we find that transcriptional cofactor HOPX is upregulated in mouse models and in human YAP1-fusion induced ependymoma, supporting their similarity." (PMID 32404936, 2020). "Interestingly, we found that HOPX was expressed in the three YAP1-MAMLD1-induced human ependymoma, while largely absent in three C11orf95-RELA-induced ependymoma." (PMID 32404936, 2020).
flu (1 paper, 2021). "We noted increased expression of genes related to cytotoxicity, activation and inflammation—such as GZMB, GNLY, TYROBP, HOPX, and CCL5—in the CD8 EMRA-like two cluster that was expanded in CAP-flu." (PMID 34424199, 2021).
lung diseases (1 paper, 2018). "Thus, we next sought to investigate the expression changes of HOPX in fibrotic lung diseases using the FCM analysis." (PMID 30154568, 2018). "HOPX contributes to alveolar injury/repair process in fibrotic lung diseases, but fails to regenerate alveolar epithelium in IPF, due to loss of HOPX." (PMID 30154568, 2018). "However, the cell function of HOPX-expressing cells in adult fibrotic lung diseases has not been investigated." (PMID 30154568, 2018).
lymphoma (1 paper, 2013). A malignant (clonal) proliferation of B- lymphocytes or T- lymphocytes which involves the lymph nodes, bone marrow and/or extranodal sites. "SU-DHL-5 showed remarkably high levels of HOPX expression as indicated by profiling data and confirmed by RQ-PCR results of lymphoma cell lines." (PMID 23637834, 2013).
malignant melanoma (1 paper, 2023). "Overall, we confirmed the practical importance of HOPX in suppressing the development of human malignant melanoma cells, as well as its diagnostic and prognostic value in SKCM patients." (PMID 37344870, 2023).
Obesity (1 paper, 2023). Accumulation of substantial excess body fat. "This did not result in an effect of obesity on the mRNA expression levels of LGR5+ (active) ISCs or HOPX (quiescent) ISCs." (PMID 38125020, 2023).
ovarian carcinoma (1 paper, 2016). A malignant neoplasm originating from the surface ovarian epithelium. "These multiple lines of evidence suggest that HOPX may be a great target for further functional validation to understand the maintenance of tumor-associated stroma along with understanding the clinically relevant “mesenchymal” subtype in ovarian cancer." (PMID 27287041, 2016). "In our further analysis of HOPX, we observed that HOPX is one of the top candidate expression regulators for ovarian cancer." (PMID 27287041, 2016).
ovarian tumors (1 paper, 2016). "This may also reflect different roles for HOPX in ovarian tumor-associated stromal tissue." (PMID 27287041, 2016).
pancreatic adenocarcinoma (1 paper, 2012). "Two cell lines of pancreatic adenocarcinoma such as PANC-1 and MIA Paca2 cells were transfected with pcDNATM3.1-HOPX with V5-tagged and established stable HOPX-expressing cell lines." (PMID 22958219, 2012).
uterine cancer (1 paper, 2009). Primary or metastatic malignant neoplasm involving the uterine corpus and/or the cervix. "Interestingly, uterine expression of HOPX in the progesterone receptor knockout (PRKO) mouse has been found to be increased by injection of progesterone; a steroid hormone known to decrease the risk of developing uterine cancer." (PMID 19200380, 2009).